SNORD115-11 (small nucleolar RNA, C/D box 115-11)
Synonyms: HBII-52-11
Gene: Small nucleolar RNA gene on chromosome 15 (25,189,414 to 25,189,495, forward strand). Ensembl gene ENSG00000200486.
Gene Ontology:
Biological process: RNA processing
Cellular component: nucleolus
Homologues: Orthologues: macaque SNORD115 (100% identical). Paralogues in human: SNORD115-29 (100% identical), SNORD115-36 (100% identical), SNORD115-43 (100% identical), SNORD115-12 (99% identical), SNORD115-16 (99% identical), SNORD115-22 (99% identical), SNORD115-26 (99% identical), SNORD115-39 (99% identical), SNORD115-44 (99% identical), SNORD115-6 (99% identical), SNORD115-9 (99% identical), SNORD115-10 (98% identical), and 37 more.